CD163 (CD163 molecule)
Diseases named in the same sentence as CD163 in open-access papers (continued):
Sharing a sentence is not in itself a finding about the gene and the disease.
tumor (continued). "The TAMs are primarily present in the tumor stroma, and POSTN encourages CD163+ macrophages to release various cytokines, including Treg-related chemokines (CCL17 and CCL22)." (PMID 37525217, 2023). "Tumor samples were stained for CD68+, CD163+, and CD206+, and CSF1R expression was used to determine the phenotypic expression of cells present in the tumor." (PMID 36769180, 2023). "We observed that, in biologically old patients, a lower infiltration of CD163+ macrophages as well as CD4+ and CD8+ lymphocytes was found in the tumor microenvironment." (PMID 37568649, 2023). "We utilized IHC staining to detect the expression of the tumor proliferation marker Ki67, the microangiogenesis marker CD31 and the M2 macrophage marker CD163 in tumor tissues." (PMID 37081748, 2023). "In the tumor microenvironment (TME) of HNSCC in biologically old patients, lower numbers of CD163+ (type 2 or M2) macrophages, CD4+ and CD8+ lymphocytes were found." (PMID 37568649, 2023). "In addition, CD163 and CD204 (molecular markers of M2 macrophages) in M2 macrophages are closely associated with histologically aggressive characteristics and a worse TNBC prognosis.TAMs can also reduce the effector function of TILs and promote Tregs to promote tumor growth and progression." (PMID 37512096, 2023). "Their results showed that the higher ratio of CD163+/CD68+ macrophages in the stroma, tumour, and total tumour tissues was significantly correlated with a higher stage and grade." (PMID 37052868, 2023). "The BLR and SLR showed significant positive correlations with the grades of CD163 cell and CD8 cell infiltration in the tumor tissue, respectively (p < 0.05)." (PMID 36983926, 2023). "In contrast, we observed a significant reduction in M1 gene markers in the spleens of tumor-bearing mice, whereas inconsistent changes were observed for the M2 markers (higher levels of Arg1 and lower levels of CCL2 and CD163)." (PMID 37628775, 2023). "Double staining for CD163 and TREM2 revealed a population of TREM2+ macrophages distributed in the tumor stroma and within tumor nests." (PMID 37370706, 2023). "Using the Lunaphore COMETTM spatial multiplex platform, we further evaluated the immune spatial landscape in 2 GBM patients by staining for B cells (CD20+), T cells (CD8+), myeloid cells (CD163+), epithelial cells (CD31+), tumor cells and astrocytes (GFAP+)." (PMID 38268923, 2023). "In the MC38 CRC murine model, selective inhibition of CSF1R reduces the number of CD163+ macrophages and increases the number of cytotoxic CD8+ T-cells within the tumor, thereby delaying tumor growth." (PMID 36765929, 2023). "The type and spatial distribution of the immune infiltrate in EOC was assessed by IHC upon staining for CD3, CD20 and CD163 on the whole cohort, and by flow cytometry by CD3, CD19 and CD33 on 19 freshly processed tumor samples." (PMID 37868997, 2023). "On the other hand, M2 macrophages express markers such as CD163 and CD206 and can exert tumour promoting functions." (PMID 37108548, 2023). "Compared to adjacent normal brain tissue, MS4A7 was typically enriched in GAMs within the tumor mass, with close relation to macrophage/microglia marker CD68 and M2 marker CD163." (PMID 36944954, 2023). "Retrospective research of patients with advanced OC examined the expression of TAMs in tumor tissues using CD68 and CD163 as M1 and M2 macrophage markers, respectively." (PMID 37298230, 2023). "Consistently, the features for suppression of anti-tumor immunity were dominantly elevated in the CDC20-high group, such as BTLA, CTLA4, CD4, ITGAM, C4B, CD163, and CD206." (PMID 37528490, 2023). "Differential expression analysis revealed significantly elevated protein expression for PD-L1 and Tim-3 in tumor segments as well as for CD127 and CD163." (PMID 38044986, 2023). "Overexpression of ZIC2 induced tumor growth in vivo, with the increase of JUNB, MCSF secretion, and CD163." (PMID 37479694, 2023).
tumor (continued). "In biologically old patients, a lower infiltration of CD163+ macrophages (p = 0.036) as well as CD4+ (p = 0.019) and CD8+ (p = 0.026) lymphocytes was found in the tumor microenvironment." (PMID 37568649, 2023). "Next, we performed a Kaplan–Meier analysis of the groups with a high and low number of CD68-, CD163-, and CD204-positive macrophages in both tumor areas." (PMID 36690825, 2023). "Tumor-promoting TAM2 are generally defined by the expression of scavenger receptors (e.g., CD204, CD206, CD163 or CD169) or ARG1." (PMID 36845555, 2023). "The macrophages in these clusters exhibited diverse expression patterns, such as inflammatory marker CD38, as well as ones corresponding to a pro-tumor (CD163, CD204, CD206) and anti-tumor (CD169) phenotype." (PMID 37190141, 2023). "CD68loCD163hi cells predominantly consist of DCs, are relatively uniformly distributed in the tumor stroma, express relatively little PD-L1 compared with the other two CD68/CD163 subsets, and interact rarely with PD-1-expressing T cells." (PMID 38322012, 2023). "The results demonstrated that tumours with high cytoplasmic S100A2 were enriched for infiltration of CD3+FOXP3+ cells (positive, P < 0.001) and CD163+ cells (positive, P = 0.009)." (PMID 37476187, 2023). "After 15 days of treatment, E-cadherin, CD68, and CD8 were increased, while vimentin, STAT3, NF-κB, CD163, and CD25 were reduced (as detailed in Table Expression, B and 8 A) in tumours of Balb/c mice when compared to the control group." (PMID 36857852, 2023). "As biomarkers for the tumor microenvironment (TME), CD163 and CD68 (tumor-infiltrating macrophages—TAM), as well as CD34 and CD105 (intratumoral microvascular density—IMVD), were chosen." (PMID 37296922, 2023). "In some of these patients, we will also study the relationship between circulating sCD163 and CD163 expression in tumor tissue." (PMID 36765852, 2023). "Compared to 2D-4-culture, a greater proportion of CD163 + and FAP + cells were exhibited in 3D-4-culture, similar to what occurs with tumor infiltration in HNSCC as well as a notable increase in the passage of HUVECs through compartments." (PMID 37907991, 2023). "Tumor ROIs in BM-LUAD expressed higher expressions of CD14, CD163, GZMA, BCL-6, BAD, BCLXL, 4-1BB, VISTA, and IDO1." (PMID 37061716, 2023). "Our results coincided with the previous reports that tumours exhibiting high levels of CD68+ and CD163+ cells correlate with increased LNM, extracapsular extension, and advanced stage in HNSCC." (PMID 35963900, 2023). "This is consistent with histomorphology in the invasive front TME, where tumor cells are surrounded by α-SMA+ CAFs, and CD163+ MØs hinder intratumoral immune infiltrate." (PMID 37254126, 2023). "With the changes in the degree of differentiation of tumor cells in CRC tissues, the number of FoxP3+ Tregs, CD163+ TAMs, and CD66b+ TANs cells changed significantly (P < .05)." (PMID 37232465, 2023). "The mean frequency of TAMs positive for CD14 or CD163 in the intratumoral stroma and CCL2+ tumor epithelial cells was higher in recurrences than in the corresponding primary tumors." (PMID 37208442, 2023). "The correlation factor between invasion front and tumor center for CD4+ lymphocytes, CD8+ lymphocytes, CD68+ macrophages, CD163+ M2-macrophages and M1-macrophages were 0.3841, 0.6587, 0.5831, and −0.0658 respectively." (PMID 36836239, 2023). "PD-L1 is expressed mainly by aggressive primary tumor cells and by CD68/CD163-positive M2 macrophages in patients with colorectal cancer with high microsatellite instability." (PMID 37525217, 2023). "Within all leukocytes (CD45+ leukocytes and CD68/CD163 subsets combined), CD45+ leukocytes generally had the highest cell density relative to total cell density (16.0 - 45.5% in tumor nests or squamous epithelium and 85.2 - 96.2% in stroma)." (PMID 38322012, 2023).
tumor (continued). "As concerns macrophages, we observed an increased number of CD68+CD163+ and CD68+IDO1+ cells in MUC1H tumor samples, revealing that TAMs were M2-polarized and able to produce KYN." (PMID 36902242, 2023). "Expression of CD163 and TIGIT was significantly higher in patients with a more aggressive and invasive tumor subtype." (PMID 37876933, 2023). "More CD163+ cells were found in high CAP2 expression tumor tissues, while there were more iNOS+ cells in low CAP2 expression tumor tissues, suggesting that CAP2 promotes M2 polarization but does not affect the chemotaxis of macrophages." (PMID 37707957, 2023). "In this study, differences were observed in PD1 expression on effector memory CTLA4lowCD103lowCD8+T cells, in CD163 and CD25 expression on type 1 CD141+CD123loDCs, and in a range of markers expressed on monocytes/macrophages and tumor cells." (PMID 37894472, 2023). "Spatial analyses uncovered a significant spatial interaction between α-SMA+ fibroblasts and CD163+ MØs in the TME, which resulted in spatially exclusive interactions to anti-tumor immune cells." (PMID 37254126, 2023). "In constant, M2 macrophages express the surface markers of CD163, CD86, and CD206 (MRC1, mannose receptor C-type 1), secrete cytokines including IL-10, TGF-β, and IL-6, and function in wound repair and tumor growth." (PMID 37749600, 2023). "As a result, we found that CD163, CD74, S100A4, S100A12, HLA-DRA, and HLA-DRB1, which are usually highly expressed in myeloid cell, were also highly expressed in tumor cells of cluster 6; thus, we termed this cluster myeloid-like tumor cells." (PMID 37138326, 2023). "The favorable involvement of CD4+ T regulatory cells and the unfavorable involvement of CD163+ TAMs and CD73+ tumor cells were also presented to correlate with the pCR rate." (PMID 36769287, 2023). "Tumor tissues from HCC patients were probed with anti-ALDOA, anti-CD68, anti-CD163, anti-CD4 and anti-FOXP3 antibodies." (PMID 36937389, 2023). "Paraffin-embedded tumor samples were stained immunohistochemically for CD3, CD20, CD38, CD56, CD66b, CD117, and CD163 and XIAP." (PMID 36472768, 2023). "Representative M2 markers include ARG1, CD163 and CD206, and the infiltration of M1 within the tumor is closely related to the poor prognosis of the tumor." (PMID 37762054, 2023). "TMAs from HNSCC, CIS, and tumor-free samples were therefore stained sequentially with antibodies against CD68, CD163, CK, CD3, PD-1, and PD-L1." (PMID 38322012, 2023). "In the tumor nest, both CD64+CD68-CD163- and CD64+CD68+CD163- TAM were detected, while CD64+CD68+CD163+ TAM were concentrated within the tumor stroma and the peritumoral area, mostly in the T-cell enriched area." (PMID 37691949, 2023). "We identified higher proportions of CD163+ and CD68+163+ TAMs in tumour tissue than in healthy adjacent tissue (t test, p < 0.01)." (PMID 35963900, 2023). "They decreased toward the IM, whereas M2‐like (CD68+CD163+ and CD68+CD163+CD206+) TAM levels were less dense and restricted to the tumor margins." (PMID 36998102, 2023). "For the TNBC cohort, the top five favorable prognostic markers were Lymph: PD-L1 ratio, Lymph: PD-L1 proportion, Tumor: CD8 proportion, Tumor: CD8 purity, and Lymph: CD163 proportion." (PMID 36707660, 2023). "A study analyzed tumor species from patients with OSCC confirmed the key roles of CD68+ and CD163+ TAMs in the progression and poor prognosis of tumors." (PMID 37221555, 2023). "CD163 is a known marker expressed in M2 macrophages, while KDM2A is highly expressed in both tumor cells and CAFs." (PMID 37821959, 2023). "In the tumor center and in the tumor periphery, the CD68+CD86+MRP8-14neg M1, CD68+CD163+ CD206neg M2, and CD68+CD206+CD163neg M2 macrophage subtypes were far from the MCs." (PMID 37637998, 2023). "The cell density of the thus defined CD68/CD163 subsets, CD45+ leukocytes and keratinocytes or HNSCC (CK+) in squamous epithelium or tumor nests and stroma was then determined." (PMID 38322012, 2023).
tumor (continued). "The higher expression of CD68, CD163, CD206 on CD45/CD14+ cells in the 4-culture PANC-1 spheroids suggest a monocytes differentiation into M2-like macrophages, known to have tumor supporting functions." (PMID 37519820, 2023). "Remarkably, we also found that the distance metrics in the MPMs revealed that mostly CD68+CD163+MRP8-14negCD86neg and M2c macrophages expressing CD68+CD163+Arg-1negMRP8-14negCD86neg were present in the tumor mass." (PMID 37958292, 2023). "According to RT-qPCR analysis, the expression of the pro-tumor macrophage markers CD206, CD163, IL-6, IL-10, Arginase-1, and TGF-β were downregulated compared to the normal control group." (PMID 38098044, 2023). "Although CD204, CD206 and CD163 are commonly used as markers for tumor-promoting TAM, the exact role of these receptors in tumor promotion is not well understood." (PMID 36845555, 2023). "Tumor progression can result from an increased proportion of M2-like TAMs containing CD68+ and CD163+." (PMID 37894541, 2023). "At the same time, the density and intensity of CD206 and CD163 in ICC tissues were higher than those in normal tissues, and they were obviously expressed in tumor stroma." (PMID 38124204, 2023). "Despite a greater proportion of M1 macrophages in the TME, M2 macrophages expressed higher gene level of CD163, MRC1 (CD206), TGF-β, IL10, VEGFA, and MMP9, which exhibited stronger tumor-promoting ability." (PMID 35033156, 2022). "Depending on the PD-L1 expression, we assessed the tumor immune features depending on CD8/PD-L1 and CD163/PD-L1 status combinations." (PMID 35681497, 2022). "Analysis of brain slices showed incorporation of MVs into microglia present in the tumor, which had reduced expression of anti-inflammatory, and thereby anti-tumor genes, such as arg1, CD206 and CD163." (PMID 35813501, 2022). "Compared with several other tumor types, we found an inverse relationship between MKNK2 and the M2 markers CD163 and MRC1 (CD206) in human PDAC tumors." (PMID 35380995, 2022). "TAMs in ascites are polarized into the M2 phenotype by expressing M2 markers, mainly CD163 and CD206, and promote tumor cell invasion and chemoresistance." (PMID 35682890, 2022). "These polarized TAMs usually express M2 macrophage markers and cytokines, such as mannose receptors (CD206), scavenger receptor (CD163), VEGF, and IL-10, and exhibit tumor-supporting effects, and are hence called M2-like TAMs." (PMID 35844605, 2022). "CXCL10 and CCL2 were also found in the tumor and TME, where they co-localized with Nestin+, Iba-1+, CD163+, or CD16+ cells, suggesting that they had a similar distribution and location." (PMID 35269652, 2022). "CAM-type macrophages express MHC II, CD86, NO, iNOS, showing the characteristics of pro-inflammatory response and anti-tumor, while AAM-type macrophages express IL-10, arg-1, CD206, CD163, TGF-β, showing immunosuppressive and tumor-promoting characteristics." (PMID 36439090, 2022). "First, we compared the internal areas of the primary tumor and liver metastases, found that 8 markers (CD8, Foxp3, CD68, CD163, CD20, CD11c, VEGFR-2, PD-L1) had higher expression in TF than TC region in both primary tumor and liver metastases (p < 0.05)." (PMID 36195882, 2022). "Correlation analysis of the markers COX2, VEGF, Ki-67, CD163, CD68, GM-CSF and M-CSF with age, tumor volume, and hearing class were performed using Spearman’s rank correlation coefficient." (PMID 36139588, 2022). "Considering immune infiltration, tumour areas with a higher FDG uptake had higher levels of T-lymphocytes (CD3+ and CD4+/CD8+) and macrophages (CD68+/CD163+) compared to areas with a lower uptake." (PMID 36143097, 2022). "Analogous to this, tumor regions with low levels of CD8+ cells were characterized by low densities of FoxP3+ and CD163+ cells." (PMID 36551693, 2022).
tumor (continued). "We confirmed the restriction of SOX2 expression to tumor cells, PTPRC/CD45 to immune cells, SPI1/PU.1, CD68, and CD163 to ‘macrophages’, CD3G to ‘T cells’, and OLIG1/2 and MBP to oligodendrocytes." (PMID 35973991, 2022). "Both tumoricidal M1 and tumor-promoting M2 macrophages express CD68, while M2 polarization can be identified by CD163, CD204 and CD206 biomarkers." (PMID 36686729, 2022). "CD163+ TAMs produced tumor-supporting cytokines (IL-6 and CXCL2) activated STAT3 in tumor cells and supported tumor progression." (PMID 36686729, 2022). "The mIF staining of CD8+ T cells and ELF4+CD163+ macrophages showed high infiltration of ELF4+CD163+ macrophages and low infiltration of CD8+ T cells in the tumor tissues of PD patients." (PMID 36209117, 2022). "All four TAM markers were significantly and positively associated with higher TIL density (p < 0.001), higher PD-L1 expression in tumor (p < 0.001) and stromal cells (p < 0.001 for CD68, IRF8 and CD163; p = 0.002 for CD206)." (PMID 36230752, 2022). "In the study, it was possible to identify TAM both in micro- and macrodissected tissue by including the macrophage-specific marker CD163, and further, to stratify the influence of TAM in the tumor microenvironment and its correlation to TYMP expression." (PMID 35567733, 2022). "Together, these observations suggest that the immune system is successfully mounting an attack against tumor cells (cytotoxic T cells, M1 macrophages), despite tumor cell PD-L1 expression and presence of M2 macrophages (CD68 and CD163)." (PMID 35379804, 2022). "IHC assays showed that M2 macrophage marker CD163 in infiltrating immune cells and MADCAM1 in the tumor cells was significantly positively stained in GC samples carrying mutated MADCAM1." (PMID 35449126, 2022). "The number of tumor-infiltrating CD4+, CD8+, Foxp3+lymphocytes, CD68+, CD163+macrophages in pre-treatment endoscopic biopsy samples were evaluated to investigate their predictive value for multidisciplinary treatment." (PMID 35658848, 2022). "In contrast, CCL18+ macrophages showed a dominant M2-like phenotype with the high expression of CD163, MARCO, and CSF1R, suggesting their stronger tumor-promoting role than SPP1+ macrophages." (PMID 35347134, 2022). "Through tumor microenvironment (TME) analysis, we found a potential influence of CD163 on immune cell infiltration." (PMID 36551651, 2022). "We found prognostic significance of the CD68, CD163 and CD8-positive cell number in the tumor stroma." (PMID 35884821, 2022). "Tumor cell-macrophage hybrids express both macrophage (CD14, CD68, CD163, CD204, and CD206) and tumor-specific markers (ALCAM, MLANA, KRT, EpCAM, CXCR4, and CD44)." (PMID 35242760, 2022). "The distribution of immune cell density showed a wider interquartile range (IQR) for all tumour regions (CT, FR, ME) than in the normal colorectal epithelium for all assessed antigens (CD8, GZMB, CD68, CD163)." (PMID 36114487, 2022). "Throughout the TME (adjacent brain/infiltrating edge, tumor, and regions of necrosis), CD3+p-STAT3– T cell/CD163+pSTAT3– macrophage clusters were significantly more common in brain metastases (P = 0.024, P = 0.01, and P = 0.045, respectively)." (PMID 35316217, 2022). "Meanwhile, matched tumor sample showed high levels of SSR2, Iba1 (26.5%), and TMEM119 (39.5%), and moderate levels of CD206 (8.81%) and CD163 (11.9%)." (PMID 35534852, 2022). "As with recent studies, CXCL13/CD163 double staining results confirmed that CXCL13 is secreted by a variety of cells within the TME, including tumor cells and tumor-infiltrating immune cells." (PMID 35570844, 2022). "In mouse model of H22 tumor cells, lncRNA CENDE downregulated the expression of CD163, STAT-6, and VEGF by promoting M2 polarization, thus indirectly regulating tumor angiogenesis." (PMID 35145526, 2022).